IL6 (interleukin 6)
Diseases named in the same sentence as IL6 in open-access papers (continued):
Sharing a sentence is not in itself a finding about the gene and the disease.
peritonitis (continued). "During peritonitis mesothelial cell-derived IL-6 interacts with soluble IL-6 receptor shed from neutrophils and the complex activates mesothelial cells to produce VEGF." (PMID 30534087, 2018). "Elevated levels of IL-6 were found in spent effluents from all patients on the first day of peritonitis, with similar values in IP samples and in the EP sample." (PMID 29850544, 2018). "Using the cecal ligation puncture model of peritonitis, it has been postulated that high levels of IL-6 in the early stages of infection are a marker for a bad prognosis for the outcome of the disease." (PMID 26126119, 2015). "The dog with peritonitis exhibited increased intracytoplasmic levels of IL-6, IL-12, IL-17A and TGF-β, whereas the dog with dermatitis presented increased expressions of IL-1α, IL-12 and TGF-β in lymphocytes." (PMID 26362860, 2015). "Analysis of IL-6 AR as well as sensitivity analyses in a peritonitis-free cohort yielded comparable results." (PMID 24410736, 2014). "Similar results were obtained when analyses were repeated in the peritonitis-free cohort as well as when IL-6 AR was analysed as the outcome." (PMID 24410736, 2014). "It confirmed that IL-1, TNFα, IL-6, IL-10 and IFNγ are present at high concentrations in the peritoneal fluid of patients with peritonitis." (PMID 24674057, 2014). "In septic patients undergoing re-laparotomy for severe peritonitis, endotoxin, tumour necrosis factor alpha, interleukin-1 and interleukin-6 levels, were higher in the peritoneal cavity then in plasma." (PMID 24674057, 2014). "Our results confirm that IL-1, TNFα, IL-6, IL-10 and IFNγ are present at high concentrations in the peritoneal fluid of patients with peritonitis." (PMID 24028733, 2013). "Consistent with other previous reports, our data showed that PDE levels of TNF-α and IL-6 were markedly elevated on the first day of peritonitis." (PMID 23359306, 2013). "Peritoneal and plasma cytokines (interleukin (IL) 1, tumor necrosis factor α (TNFα), IL-6, IL-10, and interferon γ (IFNγ)) were measured in 66 patients with secondary peritonitis." (PMID 24028733, 2013). "In parallel analyses, we examined both TNF-α and IL-6 levels in PDE of the first day of peritonitis by ELISA." (PMID 23359306, 2013). "KCs have been implicated as major producers of circulating anti-inflammatory cytokines, including interleukin-6 (IL-6) and IL-10, against peritonitis and trauma." (PMID 23209344, 2012). "Increased synthesis of hyaluronan in mesothelial cell during peritonitis is attributed to their induction by proinflammatory cytokines and growth factors, in particular, IL-1β IL-6, TNF-α, TGF-β1, and PDGF." (PMID 22577250, 2012). "In order to check for appropriate cytokine responses to S. aureus, we measured Tnf, Il6, and Il10 levels by Q-PCR in the liver in the peritonitis model." (PMID 21966468, 2011). "In the dialysate of patients with PD-relatedperitonitis and in ascites of liver cirrhosis patients with spontaneousbacterial peritonitis, high levels of various cytokines including TNFα and IL-6 are found due to increasedlocal production." (PMID 18274646, 2007). "The PEPPER trial, in contrast, applies a personalized adjuvant immunoglobulin therapy (IgGAM) in postoperative peritonitis patients, stratifying treatment response according to biomarker-defined inflammation and immune status, including IL-6, HLA-DR, immunoglobulin levels, NF-κB1, and others." (PMID 41009426, 2025). "The group sampled 2 h following treatment exhibited a decrease in the concentrations of 35 proteins in animals subjected to laparoscopic lavage, while four proteins (TGFBR3, LPL, CCL2 and IL6) were found in elevated concentrations compared to time-matched peritonitis controls." (PMID 40102905, 2025).
peritonitis (continued). "On the other hand, the oil reduced inflammation in two murine models of inflammation: carrageenan-induced peacock edema (the oil reduced peacock skin thickness and expression of IL-6 and IL-1β) and thioglycollate-induced peritonitis (TNF-α, IL-1β and IL-6 levels were reduced in peritoneal fluid)." (PMID 38473970, 2024). "We found that patients with high IL-6 AR were more likely to be anuric, more prevalent in previous episodes of peritonitis, and with a longer PD duration, higher historical glucose exposure and more ultrafiltration when compared with their counterparts in the low IL-6 AR group." (PMID 36035388, 2022). "LBP suppresses the levels of serum TNF-α and IL-6 in LPS-treated mice peritonitis." (PMID 34884814, 2021). "ethanol extract could exhibit an anti-inflammatory effect by inhibiting the production of several proinflammatory mediators, including NO, TNF-α, IL-1β, and IL-6 in LPS-induced peritonitis in vivo and in vitro." (PMID 34931128, 2021). "Surgical trauma can induce increased IL-6 levels in plasma, and elevated IL-6 levels may predict surgical complications that result in peritonitis." (PMID 34801038, 2021). "In this model, peritonitis is induced by mixed intestinal flora and a cytokine response, causing ALI29, increased microvascular permeability, and the release of pro-inflammatory mediators including TNF-α, TGF-β1, IL-6, and IL-1β30–32." (PMID 32792558, 2020). "Furthermore, the anti-inflammatory properties of 4-HAB were confirmed in a mouse model of uric acid crystals-mediated peritonitis by the reduced levels of neutrophil influx, IL-1β, active caspase-1, IL-6 and MCP-1 in lavage fluids." (PMID 31979265, 2020). "In peritonitis, treatment with the extract at a dose of 500 mg/kg resulted in a lower total leukocyte count in the peritoneal fluid and blood and lower levels of IL-1β, IL-6, TNF-α and PGE-2 than the control group." (PMID 31830043, 2019). "The switch from neutrophil to monocytic cells could be abrogated by blocking IL-6 trans-signaling with the sgp130Fc protein in an acute peritonitis model and in an air pouch model of acute inflammation in mice." (PMID 31694340, 2019). "In contrast, peritonitis history was statistically unassociated with IL-6 levels (p>0.05)." (PMID 27768727, 2016). "The plasma levels of TNF-α and IL-6 continued rising after 12 h from the induction of peritonitis whereas the reduction of HRV parameters was completed in less than 10 h from the induction of peritonitis." (PMID 26779039, 2015). "The role of single proteins such as aquaporin-1 in the transport of water across the peritoneal membrane or NOS (Nitric oxide synthase) isoforms in peritonitis, as well as, IL-6 in inflammation and TGF-β in encapsulating peritonitis were explored using genetically modified mice." (PMID 26388781, 2015). "Furthermore, STIM2-deficient animals showed decreased macrophage recruitment in the model of Thg-induced peritonitis and reduced TNFα, IL-6, and IL-1β serum levels in LPS-induced inflammation." (PMID 26417434, 2015). "In fact, a retrospective observational study of incident PD patients (n = 31) receiving standard solutions reported higher baseline dialysate IL-6 concentrations in patients who developed peritonitis (58.4 ± 12.6 pg/mL) compared to those who remained peritonitis-free (20.3 ± 8.7 pg/mL, P = 0.07)." (PMID 24410736, 2014). "Change in peritoneal solute transport rate (PSTR) and peritonitis were primary outcome measures, and the utility of IL-6 and IL-6 appearance rate (IL-6 AR) in predicting these outcomes was analyzed using multilevel linear regression and Cox proportional hazards models, respectively." (PMID 24410736, 2014). "The risk of peritonitis was associated with PD solution (biocompatible solution reduced the risk) but not baseline IL-6 levels." (PMID 24410736, 2014).
peritonitis (continued). "The present study aimed to explore the capacity of dialysate interleukin-6(IL-6) to a) predict peritoneal membrane function and peritonitis in incident PD patients, and b) to evaluate the influence of neutral pH, low glucose degradation product (GDP) PD solution on dialysate IL-6 levels." (PMID 24410736, 2014). "Importantly, there was a significant positive correlation between PDE levels of HMGB1 and TNF-α, IL-6, as well as WBCs counts during peritonitis." (PMID 23359306, 2013). "At a cellular level, peritoneal mesothelial cells demonstrate impressive adaptability to peritonitis; they effectively clear contaminants into the systemic circulation by promoting margination and migration of neutrophils, and production of proinflammatory cytokines such as IL-6, IL-8 and TNF-α." (PMID 40394329, 2025). "In particular, our preliminary data show that there is a significant increase in eryptosis levels in PD patients with peritonitis and significant positive correlations between the percentage of eryptosis and all systemic inflammatory markers tested (C-reactive protein, IL-1β and IL-6)." (PMID 38673869, 2024). "Secondly, IL-6 exposure can stimulate PMCs to secrete VEGF, meaning that overexpression of IL-6 may be the causative factor on peritoneal angiogenesis especially for PD patients with peritonitis and micro inflammatory state." (PMID 32862739, 2020). "CX43/P2Y1 dependent modulation of IL-6 secretion may be partially dependent on TNF-alpha since IL-6-promoter is also activated by TNF-alpha among other stimuli explaining the sequence of appearance during peritonitis." (PMID 30735126, 2019). "Animals with peritonitis had higher levels of inflammatory proteins such as CCL3, IL17A and IL6 in abdominal fluid and serum compared to sham." (PMID 40102905, 2025). "Throughout the development of peritonitis, macrophages produce cytokines such as tumor necrosis factor (TNF)-α and interleukin-6 (IL-6), mediating and promoting pro-inflammatory responses." (PMID 38675622, 2024). "The serum levels of TNF-α, IL-1β, IL-6, and IL-10 in rats with systemic inflammation, and the levels of TNF-α in a model of acute peritonitis in rats were also investigated." (PMID 37103384, 2023). "Flow cytometry analysis of peritoneal cells and measurement of IL-6, IL-1β, and TNF-α levels in the peritoneal lavages confirmed zymosan-induced peritonitis." (PMID 36769096, 2023). "To understand the relationship between IL-6 and IFN-γ in these processes, we tracked the activity of STAT1 and STAT3 transcription factors in stromal tissue following peritonitis." (PMID 37272871, 2023). "To explore the link between IL-6 and IFN-γ in SES–induced peritonitis, we used immunodetection methods to quantify changes in their production as a response to SES challenge." (PMID 37272871, 2023). "This process requires IL-6R shedding from infiltrating neutrophils, which promotes IL-6 trans-signaling and STAT3-driven outcomes that instruct the tissue response to peritonitis." (PMID 37272871, 2023). "Dialysate levels of cytokines, such as IL-1β, IL-6, and transforming growth factor-β (TGF-β), increase markedly on the first day of peritonitis, and then their concentrations decrease gradually." (PMID 36498493, 2022). "During an acute inflammatory process such as peritonitis, natural killer (NK) cells produce inflammatory cytokines such as tumor necrosis factor alpha (TNF-α) and interleukin (IL-6)." (PMID 35329948, 2022). "The injection of MSU or CPP crystals caused a leucocyte infiltration and an increase in IL-1β, CXCL1, IL-6, TNF-α, and VEGF in lavage fluids from mice with peritonitis, which diminished in the presence of BPI." (PMID 36361854, 2022). "We now demonstrate that genetic Acly deletion specifically in macrophages does not alter inflammatory readouts in endotoxin-induced peritonitis except for splenic Il6 expression, indicating that myeloid Acly deficiency may only mildly alter local LPS-elicited inflammatory responses in the spleen." (PMID 33981315, 2021).
peritonitis (continued). "In conclusion, ATG reduces the secretion of the proinflammatory cytokines IL‐6 and TNF‐α in acute peritonitis, thereby improving the symptoms of acute inflammation." (PMID 32960513, 2020). "Our work showed that ATG can significantly reduce inflammatory cell infiltration and the secretion of IL‐6 and TNF‐α in the tissues of mice with acute peritonitis, thereby alleviating inflammation and histological damage." (PMID 32960513, 2020). "Another study showed that in a mouse peritonitis model, FICZ reduced inflammasome activation and reduced IL6, IL-1β and TNFα levels." (PMID 32439897, 2020). "V. polysphaera extract substantially reduced the levels of proinflammatory mediators such as TNF-α, IL-1β, IL-6 and PGE-2 in λ-carrageenan-induced peritonitis when compared to the stimulated and untreated group." (PMID 31830043, 2019). "The protective effects of IRW against LPS-induced peritonitis in a rat model were explored by examining the levels of WBCs, TNF-α, and IL-6." (PMID 30719449, 2019). "It has been well described that leukocyte recruitment and inflammation maintenance involve proinflammatory cytokines such as IL-1β, IL-6, and TNF-α in zymosan-induced peritonitis." (PMID 31236418, 2019). "The differences between a peritoneal inflammatory recognized marker, IL-6, and CCL18 during peritonitis episodes should be remarked." (PMID 29850544, 2018). "On the basis of the finding that knockdown of SLC15A3 decreased TLR4-dependent IL-6 and TNF-α production, SLC15A3 was found to increase in mice with peritonitis, which was positively related to the development of inflammation." (PMID 29991810, 2018). "In the peritonitis mouse model induced by intraperitoneal injection of MRSA, MCL also suppressed the over-expression of inflammatory cytokines (IL-6, TNF-α, MCP-1 or IFN-γ) and relieved organ damage of liver and kidney." (PMID 28165033, 2017). "Gene expression profiles were similar between epididymal and subcutaneous adipose tissue depots in the mouse peritonitis model (PYCARD, IL-6, adiponectin, AdipoR1, visfatin, and LOX-1)." (PMID 28428684, 2017). "In the acute peritonitis mouse model, MCL reduced the secretion of IL-6, TNF-α, IL-1β, MCP-1, IFN-β and IL-10 in sera, and ameliorated lung and liver damage." (PMID 26984741, 2016). "Peritonitis due to ΔbgsA led to an excessive induction of TNF-α, IL6, and MIP-2 accompanied by a higher influx of leukocytes in the peritoneum and to increased mortality of infected mice." (PMID 26172831, 2015). "This is the first study to examine the impact of biocompatible solutions on the utility of IL-6 in predicting PSTR and peritonitis." (PMID 24410736, 2014). "The release of pro-inflammatory mediators can cause acute lung injury and it has been reported that levels of pro-inflammatory cytokines such as IL-6 and TNF-α are significantly elevated in the lungs after CLP-induced peritonitis." (PMID 24830455, 2014). "The present investigation is the first study to examine the impact of biocompatible PD solution use on the utility of IL-6 as a predictor of higher PSTR and peritonitis in incident PD patients." (PMID 24410736, 2014). "Levels of TNF-α and IL-6 in PDE of controls were almost undetectable, whereas levels of both cytokines markedly elevated in peritonitis patients." (PMID 23359306, 2013). "Further, there was a significant positive correlation between HMGB1 levels and WBC counts (r = 0.86, P<0.01), TNF-α level (r = 0.75, P<0.01) as well as IL-6 level (r = 0.81, P<0.01) in PDE of patients with peritonitis." (PMID 23359306, 2013). "Apart from hyaluronan, mesothelial cells also synthesize and secrete TGF-β1, IL-1β, IL-6, and TNF-α and their levels are increased during peritonitis." (PMID 22577250, 2012). "Our data showed that the survival and the serum concentrations of IL-6 and TNF-α were all enhanced by NCTD significantly in peritonitis mouse model." (PMID 22984593, 2012).
peritonitis (continued). "Additionally, Caulerpa mexicana extracts have shown the ability to reduce pro-inflammatory cytokines such as IL-6, IL-12, TNF-α, and IFN-γ in a zymosan-induced peritonitis mouse model." (PMID 40142455, 2025). "In the peritonitis mouse model characterized by a macrophage phenotype, DW18134 effectively reduced the behavioral score of the peritonitis mice and the secretion of inflammatory factors TNF-α, IL-6, and IL-1β in the serum, with therapeutic efficacy comparable to PF-06650833." (PMID 38675622, 2024). "In contrast, there was a remarkable decrease in leukocytes, neutrophils, and the expression of IL-6, IL-1β, and TNF-α in PMB-SA combination groups, indicating the attenuation of the inflammatory response in E. coli-induced peritonitis after PMB-SA combination therapy." (PMID 38258081, 2024). "In vivo analysis using a mouse peritonitis model revealed that mTNs showed anti-inflammatory effects by decreasing levels of pro-inflammatory cytokines in blood (IL-6: 73 ± 4, TNF-α: 42 ± 2%) and peritoneal fluid (IL-6: 78 ± 2, TNF-α: 21 ± 6%)." (PMID 36214916, 2022). "In the LPS-induced acute peritonitis mouse model, an increased UDPG level was found, concomitant with the expression of inflammatory cytokines (TNF and IL-6) as well as NO; however, GPI or 6AN treatment resulted in decreased UDPG levels and markedly suppressed expression of inflammatory genes." (PMID 32286295, 2020). "Moreover, acetate also suppressed the secretion of IL-6 and TNF-α in serum and IL-1β in serum and PLF during LPS-induced peritonitis." (PMID 31337751, 2019). "FTA significantly alleviated peritonitis as evidenced by the decreased number of neutrophils and levels of tumor necrosis factor alpha (TNF-α), interleukin-6 (IL-6), and monocyte chemoattractant protein-1 (MCP-1) in the peritoneal cavity, without interfering with interleukin-10 (IL-10)." (PMID 29509714, 2018). "We have previously demonstrated that different cytokines, which are present in the dialysate during peritonitis (e.g., IL-1β, TNFα, TGF-β, and IL-6) can regulate VEGF production by the mesothelium in a context dependent manner by engaging different sets of transcription factors." (PMID 30534087, 2018). "In the peritonitis mouse model, PYCARD, IL-6, and lectin-like oxidized-LDL receptor-1 (LOX-1) were significantly upregulated in epididymal and in subcutaneous adipose tissue at all time points, whereas MCP-1 was induced only in epididymal but not in subcutaneous adipose tissue." (PMID 28428684, 2017). "Baseline median dialysate IL-6 levels in patients who experienced peritonitis against those who never experienced peritonitis were, 7.87 pg/mL and 5.75 pg/mL, respectively (P = 0.15)." (PMID 24410736, 2014). "Similar to their findings, a median dialysate IL-6 concentration was greater in those who experienced peritonitis in the present study, but was not statistically significant when compared to those who did not develop peritonitis." (PMID 24410736, 2014). "Regarding the comparison to the control group, the close values for IL–6 can be noticed in the patients with peritonitis but without complications and in the control group or TNF alpha case." (PMID 21776298, 2011). "There is ample evidence thateven in the absence of peritonitis IL-6 is produced locally within theperitoneal cavity rather than transported across the peritoneal membrane." (PMID 18274646, 2007). "Firstly, they compared eryptosis levels and systemic inflammatory markers (such as CRP, IL-6, and IL-1β) in 31 PD patients with acute peritonitis and 34 PD patients with no history of systemic inflammation or peritonitis in the past three months, representing the control group." (PMID 40643488, 2025). "In addition, the concentration of pro-inflammatory cytokines TNF-α, IL-6, IL-1β, KC (CXCL1) and MIP-2 (CXCL2) within the peritoneal lavage also demonstrated that SEMA7A holds protective potential during peritonitis." (PMID 38094294, 2023).